EGFR (epidermal growth factor receptor)
Diseases named in the same sentence as EGFR in open-access papers (continued):
Sharing a sentence is not in itself a finding about the gene and the disease.
tumor (continued). "The coadministration of two drugs has a significant synergistic inhibitory effect on EGFRm tumor cells but less cytotoxicity on cells with normal EGFR or little toxic side effects on immortalized epithelial cells." (PMID 31367332, 2019). "These distinctly targeted formulations allow for the fluorescent-SERS multimodal detection of CRC markers (EGFR) and characterization of the tumor microenvironment (VEGF)." (PMID 31662751, 2019). "We selected two tumor co-culture cell models, using EGFR and EpCAM as targetable receptors on tumors." (PMID 31811202, 2019). "In the presence of EGF that is also present in the tumor microenvironment, EGFR-directed antibodies showed a paradoxical stimulatory effect on RAS mutant cells." (PMID 32039027, 2019). "EGFR-targeted interventions such as tyrosine kinase inhibitors have had limited success in CNS tumors, likely due to difficulty accessing the tumors and tumor evasion of these pathway-based drugs." (PMID 31903167, 2019). "To quantify the effect of the EGFR number on the dynamics of tumour growth, we consider tumours which consist of cells with three distinct configurations of EGFR clusters." (PMID 31016574, 2019). "EGFR TKIs have also been shown to have immunostimulatory properties (that we now understand are likely due to the tumor regression that they induce)." (PMID 31291990, 2019). "In this review, we summarized the newly updated data about immunotherapy in EGFR mutant NSCLC in term of pre-clinical study, programmed cell death protein ligand 1 (PD-L1) expression, tumor mutation burden and treatment." (PMID 31451147, 2019). "As predicted, the addition of Cilen significant enhanced the cytotoxicity of EGFR inhibitors to those integrin αvβ3+ tumor cells." (PMID 31316001, 2019). "We observed that, as previously reported, the EGFR-Pcn tumor induces overgrowth and proliferation, producing multilayered masses of disorganized disc epithelial cells and myoblasts." (PMID 31568500, 2019). "EGFR-TKI induces autophagy through the suppression of the PI3K/AKT/mTOR signaling pathway, which in turn saves tumor cells from the harm of EGFR-TKIs." (PMID 31811814, 2019). "Lastly, treatment with everolimus or AZD8055 increases epidermal growth factor receptor (EGFR) activation in tumor cells, leading to drug resistance." (PMID 31277692, 2019). "In this study, therefore, we sought to determine some of the distinct characteristics of surgically resected NSCLC patients with subsequent BM, including EGFR features, tumor stages, treatment strategies, and survival." (PMID 31048854, 2019). "These exosomes are capable of binding to the Epidermal Growth Factor Receptor (EGFR), which is expressed by many tumor cells with epithelial origin." (PMID 30940145, 2019). "Actually, EGFR signaling not only promotes proliferation and invasiveness of tumor cells directly, but also adjusts the TME by regulating macrophage recruitment and M2-like polarization." (PMID 31300030, 2019). "One cohort of mice was then subcutaneously injected in the other flank of the animal with U87 EGFR-positive tumor cells expressing truncated CD19, followed by i." (PMID 31903167, 2019). "Then, we extracted nucleic acids from different regions of tumor tissue for ARMS analysis, which revealed that only the region providing the strongest ion intensities of phospholipids for the EGFR mutation returned a positive result." (PMID 31555581, 2019). "This reflects tumor heterogeneity at a mutational and chromosomal level and the fact that the majority of advanced EGFRM+ LACs not only depends on EGFR but also on multiple co-occurring oncogenic events." (PMID 31266248, 2019). "The LDHA inhibitor Oxamate, acting via direct targeting of LDHA activity by suppressing a conversion of pyruvate to lactate, was reported to suppress cell growth in cetuximab (EGFR inhibitor) resistance HNSCC cells in vitro or to inhibit tumor growth in vivo." (PMID 31416244, 2019).
tumor (continued). "Taken together, these studies suggest that cancer immunity in the tumor microenvironment of NSCLC not only alters the efficacy of EGFR-TKIs but also the anti-PD-1/PD-L1 ICIs." (PMID 31387256, 2019). "A novel approach using chloroquine to normalize the tumor vasculature, combined with anti-EGFR aptamer-mediated delivery of erlotinib and survivin shRNA co-administration significantly hampered tumor growth." (PMID 31799190, 2019). "In light of radiation-induced tumor cell death, mitigation of radiation-induced cachexia and inhibition of tumor cell distant metastasis, the combination of TNuF and radiotherapy synergistically downregulates EGFR and VEGF signaling in NSCLC-bearing mice." (PMID 31426614, 2019). "Several clinical trials also support the idea of combined inhibition of both the VEGFR and EGFR pathways to promote more beneficial anti-tumor effects." (PMID 31699150, 2019). "Combined treatment of JQ1 with EGFR or ERK inhibitor significantly resulted in tumor growth inhibition in vitro and in vivo." (PMID 30770740, 2019). "In a spontaneous EGFR+ tumor model, an EGFR TKI had an immunomodulatory effect in addition to its direct cytotoxic effect on tumor cells and increased the number of TILs." (PMID 30621125, 2019). "The peptide is internalized by cells overexpressing EGFR and when delivered i.v. in mice it accumulates in EGFR overexpressing tumor xenografts." (PMID 30804365, 2019). "The interaction between EGFR and cancer immunity in the tumor microenvironment has been established." (PMID 31387256, 2019). "The median time from tumor diagnosis to EGFR or ALK status confirmation was 7 and 5 days, respectively." (PMID 31144459, 2019). "The short-term inhibition of tumor cell growth early in EGFR-TKI treatment is obvious, including an increase in the numbers of CD8+ T cells, DCs and M1-like TAMs, a decrease in Treg infiltration and inhibition of M1-like TAMs to M2-like TAMs." (PMID 31526368, 2019). "Circulating tumor DNA (ctDNA) is the most common source of nucleic acid for detecting EGFR and is already being implemented in clinical practice." (PMID 31582907, 2019). "Validated as robust therapeutic targets in CRC, both the vascular endothelial growth factor (VEGF) and the epidermal growth factor receptor (EGFR) are well-established mediators of tumor growth and proliferation." (PMID 30654522, 2019). "In the majority of cases, tumor development is dependent on signaling via the epidermal growth factor receptor (EGFR) and requires EGF in lower-grade forms or is EGF-independent in the more aggressive forms." (PMID 31386654, 2019). "On its part, EGFR overexpression has been shown to correlate with aggressiveness of tumors and poor survival of patients in many tumor types." (PMID 30830470, 2019). "Apatinib can significantly enhance the anti‐tumor effect of chemotherapeutic drugs or EGFR‐TKI on NSCLC." (PMID 31486270, 2019). "The importance of the EGFR/Ras/PI3K/Akt pathway in modifying the tumour microenvironment to alter radiation response has also become apparent, specifically with regard to oxygenation." (PMID 30991262, 2019). "We investigated the genomic landscape of EGFR amplification in blood-derived cell-free tumor DNA (cfDNA) across diverse cancers and the role of anti-EGFR therapies in achieving response." (PMID 31058253, 2019). "The EGFR-positive rate was 69.0% in ovarian metastases, which was concordant with the 63.6% observed in the matched primary tumours." (PMID 30858756, 2019). "The ectopically expressed EGFR in the tumor grafts was refractory to Nutlin-3a treatment and remained at a high level." (PMID 30910997, 2019). "We consider that the tumor progression is mainly driven by the EGFR/ERK pathway because it is one of the most altered in secondary tumors." (PMID 31157216, 2019).
tumor (continued). "We show that ablation of EGFR significantly suppressed tumor growth in KRAS-dependent cells and induced significantly higher expression of CX chemokine receptor 7 (CXCR7) and activation of MAPK (ERK1/2)." (PMID 30935067, 2019). "The choice of anti-EGFR antibody conjugation for the labeling of cells with AuNPs is reasoned by EGFR overexpressing in most tumor cells." (PMID 31450616, 2019). "Many patients, however, invariably experience resistance to anti-EGFR agents and have tumor progression, likely due to clonal evolution under the selective pressure of EGFR inhibition, or the acquisition of new genetic alterations." (PMID 31824558, 2019). "In vitro studies demonstrated the superior ability of FcαRI to induce neutrophil-mediated tumor cell killing for multiple tumor antigens, including EGFR, HER2, EpCAM, HLA-II, CD20, CD30, and carcinoembryonic antigen." (PMID 30984170, 2019). "Preclinical assessment of these agents revealed marked anti-tumor activity against EGFR+ cancer cell lines and xenograft models, which prompted their acceleration into clinical trials." (PMID 30975211, 2019). "Several studies documented that first-generation EGFR TKIs improve the interaction between natural killer (NK) and tumor cells favoring immune-mediated cytotoxicity, indicating that EGFR inhibitors can enhance innate tumor immune surveillance." (PMID 32082304, 2019). "The inactivating effect of melatonin on the growth of circadian-dependent tumor cells is mediated by EGFR suppression." (PMID 31123430, 2019). "EGFR expression is a marker of advanced tumor stages, resistance to standard therapeutic approaches, and reduced patient survival." (PMID 31717697, 2019). "We further compared the expression of HER2 and EGFR in primary tumours and ovarian metastases in CRC patients with ovarian metastases and their influence on prognosis." (PMID 30858756, 2019). "Combined treatment with MEKi, EGFR inhibitor (EGFRi) and PD-L1 inhibitor (PD-L1i) resulted in a marked inhibition of tumor growth in both models." (PMID 31842958, 2019). "In their study, two clinically available anti-tumor antibodies, anti-EGFR (Cetuximab) and anti-Her2 (Trastuzuab), that were conjugated by cysteine specific Click chemistry retained the specificities of both intact antibodies." (PMID 31488104, 2019). "In the present study, 16,128 tumor cells from EGFR wild-type and EGFRvIII mutant cells were profiled by scRNA-seq." (PMID 31532757, 2019). "This is particularly the case with kirsten rat sarcoma viral oncogene (KRAS), an intracellular effector molecule that routs ligand-bound EGFR to the nucleus, where it leads to constitutive phosphorylation of the receptor and hence tumor proliferation." (PMID 30800216, 2019). "It has been reported that the EGFR signalling induces tumour growth, invasion, adhesion, and angiogenesis." (PMID 30808960, 2019). "The seventh article was about EGFR and aimed to determine the clinical relevance of urinary cfDNA as an alternative source of liquid biopsy tumor biomarker." (PMID 30891428, 2019). "Characterization of the H-series OSCC cells showed less EGFR expression in H314 which originated from stage II tumor with metastasis nodes when compared to H103 which was derived from a stage I tumor." (PMID 31416147, 2019). "Until then, β-catenin is primarily located at the plasma membrane in complex with multiple cadherin family members where it drives tumor cell survival by enhancing the signaling of growth factor receptors such as EGFR." (PMID 31015417, 2019). "These trials report that EGFR inhibition by Cetuximab conferred a reduction in overall survival and tumour control when compared with cisplatin." (PMID 31308358, 2019).
tumor (continued). "For the patient-derived (xenograft) tumour cells, cisplatin yielded a modest effect (46% reduction) and the targeted-therapy (EGFR and mTOR inhibitors) revealed a strong effect (80–90% reduction)." (PMID 31331338, 2019). "Somatic mutations identified through ctDNA sequencing that match the results of multipoint exon sequencing in tumor tissues were detected, such as EGFR p.L861Q." (PMID 31822636, 2019). "We studied treatment-related structural and functional changes on tumor and immune cells in the presence of the anti-EGFR antibody cetuximab and investigated NK-mediated antitumoral activity." (PMID 31546690, 2019). "Myeloid-derived suppressor cells (MDSCs) secrete immunosuppressive factors COX2, PGE2, ARG1, and IL-6 in the tumor microenvironment to reduce the cytotoxicity of anti-EGFR target therapy in pancreatic cancer." (PMID 31387256, 2019). "In conclusion, epidermal LRIG2 excess is associated with activated EGFR/ERBB4‐MAPK signaling and accelerated tumor progression in experimentally induced NMSC, suggesting LRIG2 as a potential oncoprotein in skin." (PMID 31580518, 2019). "In contrast, all tumors, and especially cells at the tumor–stroma interface, stained strongly positive for EGFR and its downstream target pS6." (PMID 31867038, 2019). "In GBM, Src and Fyn have been found to be effectors of oncogenic EGFR signaling, which has led to tumor invasion and cancer cell survival." (PMID 30824700, 2019). "Studies have demonstrated the superior effect of erlotinib (EB) on EGFR signaling pathway blocking, which results in an obvious inhibition effect of tumor cells growth, invasion and migration." (PMID 30957572, 2019). "Ectopic expression of IFIT1 or IFIT3 in OSCC cells promoted tumor growth and metastasis by activating EGFR signaling." (PMID 31921891, 2019). "Increased expression of NRP2 results in down-regulation of EGFR, slowed tumor growth, and suppression of an EGFR “rescue” pathway of tumor cells, which is turned on as a protective response to MET-directed tumor therapy." (PMID 30717262, 2019). "The CAPRI-GOIM cohort represents a unique collection of tumor samples from mCRC patients treated with first-line anti-EGFR agents within an academic clinical trial." (PMID 31226844, 2019). "Aberrant PI3K/AKT pathway activation via activating PI3K mutations, amplification of genes encoding HER2, EGFR and AKT, BCR-ABL translocation or PTEN loss leads to decreased autophagy in many tumor cells largely through mTOR activation." (PMID 31438969, 2019). "We performed genomic analysis of intrinsic and acquired resistance to anti-EGFR therapy in prospectively collected tumour samples from 25 CRC patients receiving cetuximab (an EGFR inhibitor)." (PMID 31653970, 2019). "Since EGFRvIII is tumor-specific, a known tumor-driver, and resistant towards several EGFR-directed therapeutics, it is a perfect target for TRNT." (PMID 31374991, 2019). "Epidermal growth factor receptor is a tyrosine kinase receptor overexpressed on the surface of NSCLC tumor cells." (PMID 31123430, 2019). "The same mutation observed in the tumor was observed in the NTL of 10 patients (21.3%) of the SM group, with similar distribution for EGFR and KRAS mutations (50% of the patients each)." (PMID 30999636, 2019). "Immunohistochemical analysis showed that MGG70R (pre-dacomitinib tumour) had diffuse and intense immunopositivity for EGFR and its activated form phospho-EGFR, a very similar staining pattern to that observed in the original tumour MGG70." (PMID 30644426, 2019). "Previous studies examining the efficacy of each antibody found that the antitumor activity, especially of the anti-EGFR antibody, was affected by the primary location of the tumor." (PMID 30800219, 2019).
tumor (continued). "This, however, is in contrast to EGFR-mutated NSCLC, reported to have increased incidence of subsolid and pure ground-glass lesions and increased frequency air bronchogram in the tumor." (PMID 31861060, 2019). "Hypoxia prevented epidermal growth factor receptor (EGFR) degradation in tumor tissues, whereas activation of lysosomes enhanced tumor cell response to anti-EGFR treatment." (PMID 31717697, 2019). "In conclusion, our study showed that the detection of EGFR mutations in plasma ctDNA using either ARMS or SABER/MassARRAY is a promising, minimally invasive, and reliable alternative to tumor biopsy." (PMID 31185703, 2019). "Median EGFR expression levels were 232 amol/μg (IQR 210-299) in RAS-mutated and 192 amol/μg (IQR 165-206) in wild-type tumours." (PMID 31537838, 2019). "The conjugate links to panitumumab, which exhibits affinity to epidermal growth factor receptor (EGFR)-positive tumor cells, or to trastuzumab, which binds specifically to human epidermal growth factor receptor 2 (HER2) receptors." (PMID 31003512, 2019). "Proteomic analyses revealed that OSCC-derived EVs contain a series of tumor-associated proteins, including TRAP1, EGFR, HSP-90, and MMP-13." (PMID 30954079, 2019). "Theoretically, chemotherapy, given its different and more generic mechanism of action, can postpone the resistance to EGFR-TKIs by limiting the tumor heterogeneity, thus improving the efficacy of treatment either in first- and second-line." (PMID 31138260, 2019). "This study complements others that have shown selective and extensive tumor damage as a result of EGFR-targeted PDT." (PMID 31694307, 2019). "In the present study, we focused on the EGFR/Eps8 complex as a promising tumor target for cancer therapy." (PMID 31118055, 2019). "The FOLFOXIRI plus anti-EGFR antibodies had better results in tumor shrinkage than the FOLFOXIRI plus anti-VEGF antibodies." (PMID 30800219, 2019). "Dpp:mCherry fluorescence was present in the cytonemes of the epithelial tumor cells (2B’ and 2B”), consistent with the possibility that Dpp signaling is mediated by cytonemes in the EGFR-Pcn tumor model." (PMID 31568500, 2019). "Mutual interactions between cancer cells and the tumor microenvironment importantly contribute to the development of tyrosine kinase inhibitor (TKI) resistance in patients affected by EGFR-mutant NSCLC." (PMID 32082304, 2019). "For safety analysis, EGFR drug-related skin toxicities (RR 24.12, 95% CI 13.11–44.36; p < 0.00001) and hypomagnesaemia (RR 13.49, 95% CI 3.20–56.81; p = 0.0004) were more associated with anti-EGFR combination regimen." (PMID 31443300, 2019). "With the resulting increase in EGFR activity, we also observed a significant decrease in tumor latency." (PMID 31332182, 2019). "Generally, the germline EGFR mutations reported could be oncogenic if alone; and the growth potential would be enhanced dramatically when co-occurring with a secondary activating mutation, which may indicate a ‘second-hit’ proliferative advantage in the tumours." (PMID 31703574, 2019). "When we considered the statuses of both genes, the synergistic effects of EGFR and CCND1 were associated with tumor stage (p < 0.01), LNM (p < 0.01), and tumor differentiation (p < 0.01)." (PMID 31159251, 2019). "Combined treatment with MEKi, EGFR inhibitor (EGFRi) and PD-L1 inhibitor (PD-L1i) resulted in a marked inhibition of tumor growth in both cancer models." (PMID 31842958, 2019). "Most importantly, PKCε also plays a role in the nuclear translocation of EGFR, a main mechanism of tumor radioresistance." (PMID 30717752, 2019). "NCT503 treatment resulted in the significant tumor growth inhibition, slightly less potent than EGFR inhibition, but with minimum toxicity." (PMID 31221965, 2019).